NRXN1 (neurexin 1)
Diseases named in the same sentence as NRXN1 in open-access papers (continued):
Sharing a sentence is not in itself a finding about the gene and the disease.
amyloidosis (1 paper, 2024). A disorder characterized by the localized or diffuse accumulation of amyloid protein in various anatomic sites. "Additional astrocyte hub genes in the ETC, including NRXN1, CADM1, MACF1, MAGI2, LRP4, GJA1 and ADGRL3, have been identified as markers of a reactive astrocyte state, implicating them in amyloidosis, regulation of neuroinflammation, cellular interactions." (PMID 38913039, 2024).
Auditory hallucination (1 paper, 2025). Perception of sounds without auditory stimulus. "Although NRXN1 and its multiple SNPs are associated with both auditory hallucinations and persecutory/reference delusions, its involvement in the positive regulation of the cellular component organization pathway was observed only for auditory hallucinations." (PMID 40943654, 2025).
cervix cancer (1 paper, 2021). "NXPH1 and its two downstream receptors, NRXN1 and NRXN3, have established 1722 cell-to-cell communications, accounting for 97.6% of all possible cell-cell links in cervix cancer cell lines." (PMID 35052689, 2021).
colon cancer (1 paper, 2024). "Using an ML approach, we found that NRXN1 CND is associated with poor clinical prognosis after colon cancer resection." (PMID 39518976, 2024). "Our findings show that NRXN1 functions as a TSG in colon cancer and suggest that GSK3β inhibition is a promising therapeutic option in the context of NRXN1 knockdown; however, further validation studies are needed." (PMID 39518976, 2024). "This study provides novel insights into how NRXN1 influences colon cancer progression and highlights potential avenues for targeted therapy through the modulation of downstream signals, such as GSK3β inhibitors." (PMID 39518976, 2024). "Therefore, it is necessary to focus on the role of NRXN1 CND in colon cancer EMT and the context of chemotherapy resistance." (PMID 39518976, 2024). "Therefore, further analyses were performed to elucidate the function of NRXN1 in colon cancer tumorigenesis." (PMID 39518976, 2024). "Colon cancer samples with NRXN1 CND presented lower gene expression than those without CNV or copy number amplification." (PMID 39518976, 2024). "Therefore, we investigated the relationship between CNV and NRXN1 gene expression in resected stage II and III colon cancer samples." (PMID 39518976, 2024).
Corneal astigmatism (1 paper, 2018). "Genome-wide association studies (GWAS) for refractive astigmatism and corneal astigmatism have identified a single locus for each; in the promoter of PDGFRA (4q12) for corneal astigmatism and near NRXN1 (2p16.3) for refractive astigmatism." (PMID 30306274, 2018).
fibromyalgia (1 paper, 2021). A chronic disorder of unknown etiology characterized by pain, stiffness, and tenderness in the muscles of neck, shoulders, back, hips, arms, and legs. "Similar to DRD2, NRXN1 interacts with a range of psychiatric medications such as duloxetine, which is used for MD, generalized anxiety disorder (GAD), fibromyalgia, chronic musculoskeletal pain, and osteoarthritis of the knee." (PMID 34603368, 2021).
fragile X syndrome (1 paper, 2018). A genetic syndrome caused by mutations in the FMR1 gene which is responsible for the expression of the fragile X mental retardation 1 protein. "We did not diagnose any conditions with complete penetrance for ASD and found no cases of fragile X syndrome, but results from microarray analysis suggested a diagnosis in four children (XXY, 15q11.2 del, 1q21.1–q21.2 duplication, duplication at 2p16.3 involving NRXN1)." (PMID 29271092, 2018).
HIV encephalitis (1 paper, 2021). "This microarray study showed that neurexin 1 is downregulated in HIV encephalitis." (PMID 34610269, 2021). "Similarly, downregulation of neurexin 1, 2 and 3 were observed in disorders such as HIV encephalitis and MCI and in studies on ageing, in models of neuronal toxicity, and animal models of MS and ALS." (PMID 34610269, 2021).
infantile epileptic spasms syndrome (1 paper, 2024). "Moreover, in two siblings presenting with ASD and infantile spasms, NRXN1 exon 2–5 homozygous deletion (chr2:51149007-51255411; 106.404 kb) has been detected." (PMID 39596051, 2024).
keratoconus (1 paper, 2020). A degenerative, structural disorder of the eye, characterized by a cone-shaped protrusion of the cornea. "Specifically, we selected seven keratoconus-susceptibility genes (CDH13, SMAD3, ADAM12, CSMD1, NRXN1, CPLX2, and WWOX) for further analysis." (PMID 32737415, 2020).
narcolepsy (1 paper, 2022). A sleep disorder characterized by a tendency for excessive sleepiness during the day which occurs even after adequate sleep in the nighttime. "Later, additional self-antigens, including the neuropeptide glutamic acid-isoleucine/a-melanocyte-stimulating hormone (NEI/aMSH), the hypocretin receptor 2 (HCRTR2), prostaglandin receptor D2, and neurexin-1-alpha (NRXN1), have been identified as targets of auto-Abs in narcolepsy patients." (PMID 35445831, 2022).
Parkinson’s (1 paper, 2024). "In the context of its multiple modeling ameliorative effects, we have focused on the ameliorative effects also exerted on neurexin-1 and neuroligins in response to Parkinson’s and memory impairment, which in turn restore impairments synaptic plasticity." (PMID 38693106, 2024). "In Parkinson’s disease, treatment with Allopregnanolon (Allo) eliminated abnormalities in the electrophysiological aspects of synapses and abnormalities in the levels of the synaptic adhesion molecules PSD-95, neurexin-1, and neuroligins." (PMID 38693106, 2024).
prostate tumours (1 paper, 2021). "Next, we analyzed the bulk RNA-seq profiles of 497 patients from the TCGA cohort and detect NRXN1 expression in the majority of the prostate tumours." (PMID 34911933, 2021). "We observed an increase in the number of predicted cis-regulatory interactions around the NRXN1 locus in Gleason pattern 4 prostate tumours." (PMID 34911933, 2021). "Both our sci-ATAC-seq data and our cyclic IF results indicate NRXN1 and NLGN1 expression in immune cells infiltrating the prostate tumours." (PMID 34911933, 2021). "Finally, we observe that both NRXN1 and NLGN1 are expressed in the N-CAM positive neuronal cells within the prostate tumour stroma, with overall slightly higher expression profiles in high-risk patients." (PMID 34911933, 2021). "Our findings suggest the possibility that NRXN1 and NLGN1 expression and secretion in high-grade prostate tumours may modulate the activity between cancer cells and neurons, which may contribute to perineural invasion or neoneurogenesis in prostate cancer." (PMID 34911933, 2021).
rectum adenocarcinoma (1 paper, 2020). An adenocarcinoma arising from the rectum. "The result illustrated that the hub genes, including NRXN1, ANK2, LPHN2, APOE, TLR8, ESR1, and so on, might be critical for rectum adenocarcinoma, and m6A modification could regulate the abnormal expression of these genes." (PMID 33680913, 2020).
Rubinstein-Taybi syndrome (1 paper, 2016). A rare malformation syndrome characterized by congenital anomalies (microcephaly, specific facial characteristics, broad thumbs and halluces and postnatal growth retardation), short stature, intellectual disability and behavioral characteristics. "These include single-gene exonic deletions in NRXN1, GRM8, CREBBP (Rubinstein-Taybi syndrome, MIM:180849), KDM4B, and DMD." (PMID 27257017, 2016).
testicular cancer (1 paper, 2021). A primary or metastatic malignant neoplasm that affects the testis. "As expected, EFTUD2, ELAVL2, HNRNPD, KIT, NCL, NRXN1 and RPS8 were significantly varied in testicular cancer patients." (PMID 33746583, 2021). "Among 25 hub genes, EFTUD2, HNRNPD, KIT, NCL and RPS8 were significantly upregulated in testicular cancer patients, however, ELAVL2 and NRXN1 were significantly downregulated using GEPIA online database." (PMID 33746583, 2021).
viral infection (1 paper, 2022). "Studies of microRNAs as potential targets of treatments for viral infection have shown that miR-1290 is upregulated in SARS-CoV-2 infection, and this is predicted to result in downregulation of NRXN1 expression." (PMID 35444632, 2022).
Williams-Beuren syndrome (1 paper, 2013). "Five patients who had deletions in NRXN1 had a second CNV implicated in neurodevelopmental disorder: a CNTNAP2 and CSMD3 deletion in patients with exonic NRXN1 deletions, and a Williams-Beuren syndrome deletion and two 22q11.2 duplications in patients with intronic NRXN1 deletions." (PMID 25408897, 2013).
neurodevelopmental disorder (34 papers, 2010 to 2026). A behavioral and cognitive disorder with onset during the developmental period that involves impaired or aberrant development of intellectual, motor, or social functions. "Human genetic approaches have led to the identification of deletions and point mutations in NRXN1 in patients with autism and other neurodevelopmental disorders." (PMID 40087687, 2025). "The identification of mutations in NRXN1 associated with neurodevelopmental disorders has pointed at a hypofunction of Nrxn1 isoforms in brain diseases." (PMID 40087687, 2025). "Proper social functioning, important throughout life, is impaired in neurodevelopmental disorders of which disruptions in the genes coding for the transsynaptic communication protein neurexin-1 is a risk factor." (PMID 38418646, 2025). "NRXN1, associated with neurodevelopmental disorders, also plays a role in ASD due to CNVs in NRXN1 gene." (PMID 37807632, 2023). "Here, we highlight the functional characteristics of missense variants in NRXN1 on broad neurodevelopmental disorders." (PMID 32942984, 2020). "We knocked down the expression of PTEN and NRXN1, two genes implicated in neurodevelopmental disorders, using three complementary short hairpin RNAs (shRNA) for each gene and performing RNA-seq through the rosette stage." (PMID 31974374, 2020). "In two patients we detected de-novo CNVs encompassing genes previously associated with different neurodevelopmental disorders (NRXN1, ANKS1B, UHRF1BP1)." (PMID 29179725, 2017). "We also found two cases with ∼400kb deletions involving NRXN1, a gene previously implicated in neurodevelopmental disorders, including TS." (PMID 23533600, 2013). "Exonic deletions in the NRXN1 gene, predominantly affecting the alpha isoform, were found in patients with a range of neurodevelopmental disorders referred for diagnostic cytogenetic analysis." (PMID 25408897, 2013). "Mutations in NRXN1 are associated with autism and other neurodevelopmental disorders." (PMID 40087687, 2025). "The combined data suggest that missense variants in NRXN1 could be associated with phenotypes of neurodevelopmental disorders beyond the diagnosis of ASD and/or SCZ." (PMID 32942984, 2020). "In contrast, PFC-specific Sh-NRXN1 rats were used in our experiment, considering the special role of the prefrontal lobe in neurodevelopmental disorders." (PMID 36737720, 2023). "Another studies confirm the importance of exon deletion near the 5′ end of NRXN1 in the expression of neurodevelopmental disorders." (PMID 34357104, 2021). "NRXN1 (OMIM 600565), located on chromosome 2p16.3, is a well-established risk gene of broad neurodevelopmental disorders." (PMID 32942984, 2020). "These alterations have translational relevance to neurodevelopmental disorders for which NRXN1 deletions are a genetic risk factor, including ASD and ScZ, and to individuals with 2p16.3 (NRXN1) deletions." (PMID 31812984, 2020). "A number of genes differentially expressed in THRA mutation-containing cells, including the cell surface dystroglycan receptor NRXN1 (neurexin) and the transmembrane protein NPTN (neuroplastin), have also been implicated in other neurodevelopmental disorders." (PMID 31628250, 2019). "This case report describes a family harboring two CNV microdeletions, which affect regions of NRXN1 and MBD5 - each well-established in association with risk of ASD and other neurodevelopmental disorders." (PMID 28649445, 2017). "The importance of NRXN1 in mediating cell-cell interactions in the central nervous system, as well as its confirmed involvement in other neurodevelopmental disorders, make this gene an excellent candidate gene for TS." (PMID 23533600, 2013). "Many proteins have been identified as NRXN1binding partners, and it could be hypothesized that NRXN1 impairment will damage the protein-protein interaction, leading to neurodevelopmental disorders." (PMID 36737720, 2023).
neurodevelopmental disorder (continued). "Our data from human genetics, in vitro cell biological studies, and in silico informatics characterized NRXN1 SNVs might link to endophenotypes across neurodevelopmental disorders." (PMID 32942984, 2020). "Furthermore, our results also reinforce the need for the detailed LD mapping, CNV analysis of NRXN1 in different population or other neurodevelopmental disorders." (PMID 21477380, 2011). "This high prevalence in our SCZ cohort of relatively large ∼100–500-kb deletions, and the known involvement of germline NRXN1 mutations in SCZ and other neurodevelopmental disorders, suggests that mosaic deletions of exons 1–5 might also contribute to SCZ risk." (PMID 37601975, 2023). "Interestingly, the NRXN1-α knock-out mouse model supports the role of NRXN1 in neurodevelopmental disorders, since these mice displayed non-social behaviour as well as hyperactivity and learning deficits." (PMID 29179725, 2017).
psychiatric disorder (19 papers, 2011 to 2025). A disorder characterized by behavioral and/or psychological abnormalities, often accompanied by physical symptoms. "In sum, these findings suggest that alterations in the repertoire of NRXN1α isoforms in carriers of heterozygous NRXN1 deletions underpin perturbed synaptic function and neuronal maturation during brain development and thus may increase the risk for later major psychiatric disorders." (PMID 32033412, 2020). "This genotype-dependent mode of action of NRXN1α isoforms suggests the existence of a dominant-negative effect for specific heterozygous NRXN1 deletions in the pathogenesis of NRXN1-related psychiatric disorders including ASD." (PMID 33308283, 2020). "Among NRXN genes, NRXN1 is involved in neurodevelopmental and psychiatric disorders." (PMID 40259965, 2025). "Similarly, Sudhof and colleagues used both hPSNs and induced neurons (iNs) to model psychiatric diseases (e.g., ASD and SCZ) by creating heterozygous conditional neurexin 1 (NRXN1) mutations in human embryonic stem cells (hESCs)." (PMID 27274733, 2016). "For instance, NRXN1 is one of the most studied NDD genes in which homozygous mutations cause Pitt–Hopkins-Like syndrome 2 characterized by NDDs, such as ID and ASD52, and heterozygous deletions predispose to several NDDs, psychiatric disorders, as well as congenital malformations." (PMID 32929080, 2020).
tumor (16 papers, 2010 to 2026). "Functional experiments further showed that loss of GABRB3 or NRXN1 impaired tumor growth and brain colonization in xenograft models." (PMID 42034645, 2026). "Neurexin-1 was the only prioritised target that, when expressed at high levels in tumours at diagnosis, was associated with an adverse outcome (EFS and OS)." (PMID 34403115, 2021). "Moreover, the knockout of NRXN1 in SHP77 cells resulted in a loss of the anti-tumor activity of NRXN1-mediated ADC therapy." (PMID 33062195, 2020). "Compared with its expression in normal tissues, NRXN1 expression was lower in tumors, suggesting its potential role as a tumor suppressor." (PMID 39518976, 2024). "Several regions distal to the NRXN1 promoter and intronic sequences within the gene body that are inaccessible in Gleason pattern 3 tumours, are accessible in Gleason pattern 4 tumours." (PMID 34911933, 2021). "To validate our results that show a significant enrichment in the chromatin accessibility profiles of high-grade tumours for neuronal adhesion molecules NRXN1, NLGN1 and CDH9, we analyzed the bulk ATAC-seq profiles using the TCGA PRAD data set35." (PMID 34911933, 2021). "The functional and prognostic potential of the most significant gene (neurexin-1) was investigated using knock-down studies and immunohistochemistry of two independent tumour cohorts." (PMID 34403115, 2021). "In this cohort FFPE ES were employed to test the suitability of neurexin-1 IHC for analysis in FFPE tumours." (PMID 34403115, 2021). "We found that the expression of neurexin-1 in tumours was heterogeneous, localised to the plasma membrane, cytoplasm and occasionally the nucleus." (PMID 34403115, 2021). "Interestingly, the cell adhesion molecule neurexin-1 (NRXN1) is considered a new potential target for tumor cells." (PMID 36686667, 2022). "We therefore went on to evaluate the prognostic potential of neurexin-1 in a second tumour cohort." (PMID 34403115, 2021). "The pattern of neurexin-1 in FFPE tissues was similar to that in frozen tumours." (PMID 34403115, 2021). "Notably, genomic regions associated with the neuronal adhesion genes, NRXN1, NLGN1 and CDH9, are highly accessible in Gleason pattern 4 vs. 3 tumours." (PMID 34911933, 2021). "Since neurexin-1 dependent pathways regulate pre- and post-synaptic organisation, cell migration, motility and cell-cell adhesion, we are currently investigating their role in multicellular models and tumours." (PMID 34403115, 2021). "We herein report that NRXN1-mediated ADC exhibited anti-tumor activity in vitro, and thus NRXN1 could be a novel target of ADCs for SCLC." (PMID 33062195, 2020). "Gains in some of the genes involved in invasive/migratory properties (MGAT5, PKP4, ITGB6), cell cycle progression and regulation of apoptosis (RBMS1), and angiogenesis (NRXN1) may be involved in tumor development and progression." (PMID 26432421, 2015). "Analysis of GSE99671 revealed significantly higher expression levels of KLK2, NRXN1, HES5, OR2W3, and HS3ST4 in normal samples compared to tumor samples." (PMID 40128298, 2025). "Despite these major clinical differences in the patient data sets, we detect a significant increase in the accessibility of NRXN1 and CDH9 chromatin sites in high-grade tumours as compared to intermediate-grade tumours." (PMID 34911933, 2021). "Most ES expressed neurexin-1 (96%) and ELFN2 (96%), whereas SLC38A11 and CCDC190 were detected in just 41% and 67% of the tumours examined, respectively." (PMID 34403115, 2021). "The combination of the primary anti-NRXN1 monoclonal antibody and the secondary ADC exhibited anti-tumor activity in an NRXN1-expression dependent manner." (PMID 33062195, 2020). "The combination of a primary anti-NRXN1 monoclonal antibody and a secondary ADC exhibited anti-tumor activity in SCLC cell lines." (PMID 33062195, 2020).
tumor (continued). "The prognostic potential of neurexin-1 expression in FFPE and frozen tumours demonstrates its suitability for transfer to the clinic, where it may be used at diagnosis to identify patients with localised disease that will develop metastasis and relapse for more intensive or novel treatment." (PMID 34403115, 2021). "We also observed some additional putative regulatory interactions in Gleason pattern 4 tumours around the NLGN1 and CDH9 loci, even though the increase in the number of links were not as high as around the NRXN1 locus." (PMID 34911933, 2021).